HPS6 (HPS6 biogenesis of lysosomal organelles complex 2 subunit 3)
Description:
May regulate the synthesis and function of lysosomes and of highly specialized organelles, such as melanosomes and platelet dense granules. Acts as a cargo adapter for the dynein-dynactin motor complex to mediate the transport of lysosomes from the cell periphery to the perinuclear region. Facilitates retrograde lysosomal trafficking by linking the motor complex to lysosomes, and perinuclear positioning of lysosomes is crucial for the delivery of endocytic cargos to lysosomes, for lysosome maturation and functioning.
Synonyms: FLJ22501; BLOC2S3
Tractability: PROTAC: ubiquitination databases record sites on it; its protein half-life has been measured.
Gene: Protein-coding gene on chromosome 10 (102,065,349 to 102,068,036, forward strand). Ensembl gene ENSG00000166189.
Subcellular location: Microsome membrane; Cytoplasm, cytosol; Early endosome membrane; Lysosome membrane
Subcellular location (Human Protein Atlas): Cytosol; Vesicles
Gene Ontology:
Molecular function: GTP-dependent protein binding; protein binding; small GTPase binding; AP-3 adaptor complex binding
Biological process: lysosome localization; protein localization to membrane; melanosome assembly; platelet dense granule organization; lipid homeostasis; protein secretion
Cellular component: BLOC-2 complex; cytosol; early endosome membrane; lysosomal membrane; membrane; early endosome
Genetic constraint (gnomAD): Loss-of-function variants: 47 observed, 52.31 expected, observed/expected ratio (o/e) 0.9, 90% interval 0.71 to 1.15. The synonymous counts are far from expectation, so gnomAD's model fits this gene poorly and the ratio says little. Missense variants: 1,034 observed, 956.54 expected, observed/expected ratio (o/e) 1.08, 90% interval 1.03 to 1.14. Synonymous variants: 535 observed, 452.06 expected, observed/expected ratio (o/e) 1.18, 90% interval 1.1 to 1.27.
Gene-disease validity (ClinGen):
ClinGen rates the evidence that HPS6 causes each of these diseases.
Hermansky-Pudlak syndrome 6 (autosomal recessive): Definitive.
Homologues: Orthologues: chimpanzee HPS6 (99% identical), macaque HPS6 (97% identical), dog HPS6 (88% identical), mouse Hps6 (82% identical), rat Hps6 (75% identical), guinea pig HPS6 (74% identical), tropical clawed frog hps6 (34% identical).
Diseases named in the same sentence as HPS6 in open-access papers:
HPS6 is named in the same sentence as 21 diseases in open-access papers, as found by Europe PMC text mining. Sharing a sentence is not in itself a finding about the gene and the disease. The quoted sentences say what the papers report.
albinism (4 papers, 2020 to 2024). A congenital disorder characterized by partial or complete absence of melanin pigment in the eyes, hair, or skin. "Mutations in the HPS6 gene are known to cause reduced or diminished pigmentation (albinism) in the eyes, skin, and hair." (PMID 35054407, 2021). "The genes identified for MAC were KMT2D, MAB2IL2, ALDH1A3; ASDA were KERA, PAX6, MYOC, TGFBI, and SLC4A11; congenital cataract were CRYBB2, EPHA2, HSF4 and BCOR; infantile nystagmus were CACNA1A and FRMD7; and albinism were OCA2, GPR143, HPS6 and SLC38A8." (PMID 32830442, 2020).
oculocutaneous albinism (3 papers, 2013 to 2021). Oculocutaneous albinism (OCA) describes a group of inherited disorders of melanin biosynthesis characterized by a generalized reduction in pigmentation of hair, skin and eyes and variable ocular findings including nystagmus, reduced visual acuity and photophobia. "The HPS6 gene mutation causes HPS6, which is characterized by oculocutaneous albinism, a mild bleeding diathesis, and milder pulmonary fibrosis." (PMID 35054407, 2021). "Double homozygous mutations in HPS6 gene led to HPS6 syndrome, resulting in oculocutaneous albinism in the patient, while the parents were heterozygous carriers for both variants." (PMID 35054407, 2021). "Although no platelet and/or lysosome storage defect was detected in the patient or family, an oculocutaneous albinism diagnosis was established based on the HPS6 mutations." (PMID 35054407, 2021).
atherosclerosis (1 paper, 2016). A disease characterized by the build-up of fatty material and calcium deposition in the arterial wall resulting in partial or complete occlusion of the arterial lumen. "The defects in the secretion of HM VWF upon DDAVP treatment in the ru mice could confer the resistance for atherosclerosis in these mice or HPS6 patients." (PMID 27889498, 2016).
coagulation disorders (1 paper, 2021). "Decreased vWF secretion is also one of the reasons why HPS6 deficiency leads to coagulation disorders." (PMID 35252216, 2021).
HPS6 also shares sentences with these, for which no sentence is quoted: cancer (2 papers); Hermansky-Pudlak syndrome (2); Batten disease (1); Chediak-Higashi syndrome (1); congenital cataract (1); Congenital disorder of glycosylation, type Iq (1); congenital nystagmus (1); Griscelli syndrome (1); Hermansky-Pudlak syndrome 6 (1); Knobloch syndrome, type 1 (1); macrosomia (1); Menkes syndrome (1); oculocutaneous albinism type 1 (1); pulmonary fibrosis (1); thrombophilia (1); thrombosis (1); X-linked ocular albinism (1).